ENSG00000288674 (Novel protein)
Gene: Protein-coding gene on chromosome 1 (226,870,184 to 226,987,545, forward strand). Ensembl gene ENSG00000288674.
Genetic constraint (gnomAD): Missense variants: 522 observed, 614.62 expected, observed/expected ratio (o/e) 0.85, 90% interval 0.79 to 0.91. Synonymous variants: 255 observed, 256.63 expected, observed/expected ratio (o/e) 0.99, 90% interval 0.9 to 1.1.